JUNB (JunB proto-oncogene, AP-1 transcription factor subunit)
Description:
Transcription factor involved in regulating gene activity following the primary growth factor response. Binds to the DNA sequence 5'-TGA[GC]TCA-3'. Heterodimerizes with proteins of the FOS family to form an AP-1 transcription complex, thereby enhancing its DNA binding activity to an AP-1 consensus sequence and its transcriptional activity (By similarity).
Synonyms: AP-1
Tractability: PROTAC: UniProt records ubiquitination sites on it; ubiquitination databases record sites on it.
Gene: Protein-coding gene on chromosome 19 (12,791,486 to 12,793,315, forward strand). Ensembl gene ENSG00000171223.
Subcellular location: Nucleus
Subcellular location (Human Protein Atlas): Nucleoplasm
Pathways (Reactome):
Signal Transduction: NGF-stimulated transcription; SMAD2/SMAD3:SMAD4 heterotrimer regulates transcription
Disease: Nuclear events stimulated by ALK signaling in cancer
Immune System: Interleukin-4 and Interleukin-13 signaling
Gene Ontology:
Molecular function: protein binding; sequence-specific double-stranded DNA binding; DNA binding; DNA-binding transcription factor activity, RNA polymerase II-specific; RNA polymerase II cis-regulatory region sequence-specific DNA binding; DNA-binding transcription activator activity, RNA polymerase II-specific; DNA-binding transcription factor activity; double-stranded DNA binding; RNA polymerase II transcription regulatory region sequence-specific DNA binding
Biological process: positive regulation of transcription by RNA polymerase II; integrated stress response signaling; regulation of cell cycle; regulation of cell population proliferation; regulation of T-helper 17 cell differentiation; regulation of transcription by RNA polymerase II; response to steroid hormone; gene expression; regulation of DNA-templated transcription
Cellular component: nucleoplasm; RNA polymerase II transcription regulator complex; transcription factor AP-1 complex; chromatin; nucleus; transcription regulator complex
Genetic constraint (gnomAD): Loss-of-function variants: 6 observed, 13.76 expected, observed/expected ratio (o/e) 0.44, 90% interval 0.24 to 0.86. The upper end of that interval is the gene's LOEUF score, 0.86, which puts it in group 3 of 6, group 1 being the genes least tolerant of losing a copy. Missense variants: 389 observed, 438.61 expected, observed/expected ratio (o/e) 0.89, 90% interval 0.81 to 0.96. Synonymous variants: 226 observed, 207.18 expected, observed/expected ratio (o/e) 1.09, 90% interval 0.98 to 1.22.
Homologues: Orthologues: chimpanzee JUNB (99% identical), dog JUNB (97% identical), pig JUNB (97% identical), rat Junb (93% identical), guinea pig JUNB (93% identical), mouse Junb (93% identical), macaque JUNB (92% identical), zebrafish junba (57% identical), zebrafish junbb (53% identical), tropical clawed frog junb (49% identical), Drosophila melanogaster Jra (27% identical), Caenorhabditis elegans F19B2.6 (23% identical). Paralogues in human: JUN (46% identical), JUND (41% identical).
Diseases named in the same sentence as JUNB in open-access papers:
JUNB is named in the same sentence as 178 diseases in open-access papers, as found by Europe PMC text mining. Sharing a sentence is not in itself a finding about the gene and the disease. The quoted sentences say what the papers report.
breast cancer (34 papers, 2005 to 2025). A primary or metastatic malignant neoplasm involving the breast. "In silico analysis of available published protein breast cancer dataset using the Kaplan-Meier plots website also showed that high levels of JunB protein were associated with bad prognosis." (PMID 36494864, 2022). "Other gene found in drug resistance network is JUNB which has been associated with invasion/metastasis in breast cancer and represents an important target in diseases, associated with EMT." (PMID 33187552, 2020). "Additionally, the (CK+CXCR4+JUNB+) phenotype in bone marrow disseminated tumor cells (DTCs) of early breast cancer patients is strongly linked to poorer OS." (PMID 39575761, 2025). "In addition, CXCR4 and JUNB have been associated with poorer overall survival (OS) of early-stage breast cancer patients and lower progression-free (PFS) and overall survival of NSCLC patients." (PMID 38727318, 2024). "JunB deficiency leads to the development of acute and chronic myeloid leukemia, distant metastasis in breast cancer, and enhanced angiogenesis in prostate cancer by modulating the activity of various immune cells, such as promoting pro-angiogenic factor production by neutrophils." (PMID 37731821, 2023). "Moreover, in silico meta-analysis of JUNB protein levels showed its association with poor survival in breast cancer patients and identified a positive correlation between JUNB, CCNE1, and TGFB2 expression levels in these tumors." (PMID 36494864, 2022). "Finally, we conducted in silico analysis of clinical cancer data and show that amplification of JUNB associates with poor outcome in ovarian and breast cancer." (PMID 36494864, 2022). "In addition, there are some recent data indicating that JUNB is implicated in the earliest events of development of resistance to kinase inhibitors in breast cancer." (PMID 31370904, 2019). "Interestingly, in line with these data the presence of JUNB in breast cancer patients’ CTCs has been previously associated with significantly lower median PFS (Kaplan–Meier analysis, p = 0.015) and OS (Cox regression, p = 0.026, HR = 2.31, and Kaplan–Meier analysis, p = 0.02)." (PMID 36612166, 2022). "To assess the impact of the 3LBNC on gene expression, we evaluated the levels of E-cadherin, JUNB, and DUSP5, three genes associated with breast cancer." (PMID 40558895, 2025). "Of particular interest were three DNA-binding factors associated with AR on chromatin in all breast cancer contexts: GATA3, JUNB, and ERF." (PMID 38317241, 2024). "The change in PR activity by FGF7/FGFR/JunB also changes the response of ER+ breast cancer cells to anti-ER therapies." (PMID 39596875, 2024). "In breast cancer, JUNB and ERF are transcriptional repressors downregulated by ER signaling, a feature that facilitates ER-induced transcription of proliferation genes." (PMID 38317241, 2024). "Similar observations regarding high expression of CXCR4 and JUNB were noted in our prior investigations involving metastatic and early breast cancer patients, as well as in NSCLC patients." (PMID 38727318, 2024). "To test this idea in breast cancer cells in the present study, we force-delivered a plasmid carrying a mutant JunB that lacks DNA binding ability (JunB ΔDNA) into MDA-MB-231 cells." (PMID 37091157, 2023). "A strikingly high stromal JUNB expression in human breast cancer samples prompted us to functionally investigate the consequences of JUNB loss in cells of the tumor microenvironment on cancer progression and metastasis in mice." (PMID 34282521, 2021). "In contrast, JUNB levels were negatively correlated to tumor stage and lymph node involvement in breast cancer specimens." (PMID 34282521, 2021). "To adequately mimic the clinical situation, we applied a syngeneic spontaneous breast cancer metastasis model followed by primary tumor resection and identified stromal JUNB as a potent suppressor of distant metastasis." (PMID 34282521, 2021).
breast cancer (continued). "Here, we describe a strong JUNB expression in cells of the tumor microenvironment of human breast cancer specimens." (PMID 34282521, 2021). "To assess JUNB levels, we stained a tissue microarray of human mammary carcinoma for JUNB by immunohistochemistry." (PMID 34282521, 2021). "Functional studies have demonstrated that JUNB plays a pro-survival role in breast cancer cells in response to a lethal dose of flavopiridol." (PMID 32241272, 2020). "In MDA-MB-231 cells was demonstrated that TNF-α increased the expression profile and activity of MMP-9 by inducing JUNB DNA binding activity, thus strengthening the concept of a pro-tumorigenic effect of TNFα in breast cancer." (PMID 33187552, 2020). "Various JUN and FOS members have been found to interact with SMADs, and JUNB triggers activation of a TGFβ-induced SMAD-dependent breast cancer invasion program." (PMID 32350443, 2020). "JUNB intensity was statistically higher in all breast cancer cell lines (SKBR3: p = 0.0001, MCF7: p = 0.001, MDA-MB231: p = 0.0001) compared to normal donors’ PBMCs." (PMID 31370904, 2019). "Multivariate analysis revealed that JUNB expression in CTCs is an independent prognostic factor (p = 0.016, HR 2.2484) for OS in breast cancer patients." (PMID 31370904, 2019). "JUNB is also called Activator Protein 1 (AP-1) and is involved in skin and breast cancer development." (PMID 25475428, 2014). "The expression of the Jun proteins c-Jun, JunB and JunD as well as the Fos family members c-Fos, FosB, Fra-1 and Fra-2 in the analysed mammary tumour tissues was described in our prior publication." (PMID 15928662, 2005). "Furthermore, previous studies by our group have indicated a high expression of CXCR4, JUNB, and PD-L1 in CTCs and/or DTCs of breast cancer and NSCLC patients, related to their survival." (PMID 38727318, 2024). "The presence of JUNB in CTCs from breast cancer patients is correlated to poor prognosis." (PMID 38727318, 2024). "In addition, the presence of JUNB-positive CTCs emerged as an independent prognostic factor for OS in breast cancer patients." (PMID 31370904, 2019). "However, in the present study, the percentage of patients having CTCs with JUNB expression was higher than those with CXCR4 compared to breast cancer cases, implying that JUNB could be a very important player in metastatic procedure in NSCLC patients." (PMID 36612166, 2022). "Thus, we could use this so far only known C57BL/6-mouse-derived model of spontaneously metastatic mammary cancer to analyze the contribution of stromal JUNB to metastasis." (PMID 34282521, 2021). "Also, JUNB has been involved in the earliest events of resistance development in breast cancer." (PMID 33187552, 2020). "In breast cancer, NAT10-mediated stabilization of JunB mRNA upregulates LDHA expression, creating an immunosuppressive niche via lactate-driven inhibition of cytotoxic T cells." (PMID 40588654, 2025). "NAT10 upregulated JunB expression by increasing ac4C modification levels on its mRNA, further up-regulated LDHA expression and facilitated glycolysis in breast cancer." (PMID 40588654, 2025). "Both JunB and CXCR4 have been shown to be overexpressed breast cancer, and CXCR4 has been implicated in tumor progression in pancreatic cancer." (PMID 38835488, 2024). "It was reported that in breast cancer AP-1 transcription factor components, i.e., JUN, JUNB, FOS, FOSB, in addition to DUSP1, EGR1, NR4A1, IER2 and BTG2, behave as a conserved co-regulated network 14, most of which are transcriptional factors." (PMID 37057290, 2023). "We have previously reported that JUNB and CXCR4 are overexpressed in circulating and disseminated tumor cells from breast cancer patients and are correlated with worse survival." (PMID 36612166, 2022). "Our studies have shown that JUNB and CXCR4 are significantly overexpressed in CTCs isolated from metastatic breast cancer patients compared to normal donors’ and patients’ peripheral blood mononuclear cells (PBMCs)." (PMID 36612166, 2022).
breast cancer (continued). "Results indicate that p-S259 JunB, p-S79 JunB, and p-T512 ICAM-1 phosphoproteins were significantly upregulated in the plasma of breast cancer patients compared to healthy individuals." (PMID 36293212, 2022). "We have previously also shown that DTCs isolated from the bone marrow of early, non-metastatic, breast cancer patients also express high levels of JUNB and CXCR4, with their expression being similar or higher to other breast cancer cell lines." (PMID 36612166, 2022). "We found that JUNB copy number alterations (CNA) occur in several cancers including sarcoma, ovarian, esophagus, lung squamous carcinoma, and breast cancers." (PMID 36494864, 2022). "Earlier studies of our group in CTCs and disseminated tumor cells (DTCs) from breast cancer patients identified a new pair of biomarkers, namely the C-X-C motif chemokine receptor 4 (CXCR4) and the transcription factor JUNB." (PMID 36612166, 2022). "Indeed, by applying a syngeneic breast cancer model of spontaneous metastasis combined with surgical excision of the primary tumor to conditional KO mice with a stromal JUNB ablation, we could identify JUNB as a strong suppressor of metastasis." (PMID 34282521, 2021). "Our findings on JUNB and CXCR4 verify our prior studies on breast cancer‐derived CTCs and DTCs." (PMID 39575761, 2025). "Interaction between AR and any one of these factors has not been previously reported in the context of breast cancer, but JUNB and ERF have been identified as AR interacting proteins in two LNCaP-derived cell line models of prostate cancer." (PMID 38317241, 2024). "Both CXCR4 and JUNB are highly expressed in CTCs isolated from metastatic breast and non-small cell lung cancer (NSCLC) patients, as well as in disseminated tumor cells (DTCs) isolated from early-stage breast cancer migrated in bone marrow." (PMID 38727318, 2024). "In addition to GATA3, two other DNA binding transcription factors, JUNB and ERF, were identified as AR interacting proteins in all breast cancer cell line models." (PMID 38317241, 2024). "Smad cofactors that have been reported to be involved in TGF-β-induced cell motility or invasion include JunB in breast cancer cells, Olig1 in NMuMG cells, and Sox4 in nontransformed human mammary epithelial cells." (PMID 33741342, 2021). "In breast cancer, CXCL8 expression level strongly correlated with activating transcription factor 3 (ATF3), c-Jun and JunB, members of the AP-1 transcription factor complex, and ATF3 and JunB were also observed to be upregulated in the metastatic osteosarcoma samples investigated here." (PMID 22518090, 2012). "“All of the mouse and most human mammary tumors also displayed decreased expression of genes known to inhibit cell proliferation, including NFKBIA (IKBalpha), GADD45B, and CDKN1A (p21); transcription-related genes such as CEBP, JUN, JUNB, and ELF1;....”." (PMID 23216862, 2012). "This high expression level of both JUNB and CXCR4 was also observed in our previous studies for metastatic breast cancer patients’ CTCs (JUNB: 65% and CXCR4: 90% in patients’ cohort) and for DTCs from the bone marrow of early breast cancer patients (JUNB: 95% and CXCR4: 92% in patients’ cohort)." (PMID 36612166, 2022). "However, it is noteworthy, that although the (CK+/JUNB–/CXCR4–) phenotype was the most frequent in SCLC, none of the patients nor their CTCs had exclusively that phenotype, which was also the case in breast cancer DTCs." (PMID 36612166, 2022).
psoriasis (27 papers, 2011 to 2025). An autoimmune condition characterized by red, well-delineated plaques with silvery scales that are usually on the extensor surfaces and scalp. "Inducible epidermal deletion of JunB and c-Jun.In humans the JunB transcription factor is localized in psoriasis susceptibility locus 6 and regulates cell proliferation, differentiation, stress responses and cytokine expression." (PMID 34485340, 2021). "The inducible epidermal deletion of both c-Jun and JunB, for example, causes a psoriasis-like skin phenotype in adult mice, whereas single deletion results in no phenotype." (PMID 33758366, 2021). "FOSL1 can dimerize with Jun to form the Ap-1 complex, and the decreased activity of the pathway has been shown in a mouse model, with epidermal deletion of JunB/AP-1 causing psoriasis." (PMID 22957057, 2012). "The JunB loss in keratinocytes induces chemokine/cytokine expression, attracts neutrophils and macrophages to the epidermis, and contributes to phenotypic changes in psoriasis." (PMID 33802099, 2021). "Thus, JunB gene is located in the psoriasis susceptibility region PSORS6, and epidermal deletions of JunB and c-Jun in mice lead to psoriasis-like lesions." (PMID 30984165, 2019). "Control of JunB protein level at various steps would provide new therapeutic opportunities for human inflammatory autoimmune diseases in which Th17 cells have been implicated, such as psoriasis and multiple sclerosis." (PMID 29234109, 2017). "For instance, the epidermal-specific deletion of inhibitor of NF-kB kinase 2 (IKK2) or the double knockout of the c-Jun and JunB genes in mice resulted in psoriasis-like phenotypes in a T-cell-independent manner." (PMID 40767593, 2025). "As functionally antagonistic members of AP‐1, JunB expression is significantly decreased in lesions from severe psoriasis patients, whereas c‐Jun is barely in normal skin but obviously elevated in psoriatic epidermis." (PMID 40038877, 2025). "Genetic deletion of JunB and JunC in keratinocytes results in chemokine and cytokine overproduction and sufficiently trigger psoriasis in mice." (PMID 33990547, 2021). "Increased nuclear staining intensity of FOSL1 and JUNB within keratinocytes was observed in lesional psoriasis skin irradiated with 311 nm UVB compared to 290 nm UVB and/or unirradiated lesional control skin." (PMID 33812333, 2021). "Taken together, loss of N4BP1 results in not only abnormal keratinocyte proliferation but also abnormal neutrophil maturation and infiltration by directly controlling JunB, FosB, and CXCL1, respectively, leading to susceptibility to psoriasis." (PMID 33990547, 2021). "Topical application of dithranol ameliorates psoriasis-like skin lesions in c-Jun/JunB knockout mice." (PMID 32484435, 2020). "The therapeutic importance of reduction of IL-1 family members in human skin was substantiated by results generated in the keratinocyte-based c-Jun/JunB mouse psoriasis model." (PMID 32484435, 2020). "Serial biopsies from human psoriatic lesions and both the c-Jun/JunB and imiquimod psoriasis mouse model allowed us to study the therapeutic mechanism of this drug." (PMID 32484435, 2020). "In total, the microarray assay allowed us to compare 300 DEGs in dithranol-treated psoriasis patients (week 2–3 vs. day 0) and 18 DEGs from day 6 vs. day 0 with 336 murine DEGs from dithranol-treated c-Jun/JunB knockout mice." (PMID 32484435, 2020). "We then compared DEGs from psoriasis patients treated with dithranol to DEGs from dithranol-treated c-Jun/JunB knockout mice." (PMID 32484435, 2020). "The psoriasis‐like phenotype in DKO*‐mT/mG mice was induced by the genetic deletion of c‐Jun and JunB floxed alleles in K5+ basal keratinocytes and K5+ epidermal stem cells after tamoxifen administration." (PMID 31556482, 2019). "Overall, these data show that the specific inactivation of c‐Jun and JunB in bulge HF‐SCs is sufficient to induce a psoriasis‐like phenotype in the DKO*K15‐mT/mG mice." (PMID 31556482, 2019).